EGF (epidermal growth factor)
Diseases named in the same sentence as EGF in open-access papers (continued):
Sharing a sentence is not in itself a finding about the gene and the disease.
tumor (continued). "This study further reported that both tumor cells and TAMs release CSF-1 and epidermal growth factor (EGF), respectively, which may interact which each other and facilitate the tumor cell migration." (PMID 34207035, 2021). "Considerable evidence suggests that EGF may be one of the key factors that initiate hepatocyte proliferation, and supports a role for EGF in malignant transformation and tumor progression." (PMID 34572344, 2021). "Additionally, KCC4 and its stimulators, EGF and IGF-1, are colocalized in the metastatic cancer tissues, suggesting the cooperation between KCC4 and EGF or IGF-1 in tumor metastasis." (PMID 35008759, 2021). "Furthermore, EGF-induced linear ubiquitination was critical for tumor cell proliferation and tumor development." (PMID 34769306, 2021). "It seemed that GPRC5A could affect signaling related to hypoxia, tumor environment, Rho GTPase, NF-kB and EGF response." (PMID 33753999, 2021). "In this protocol, finely minced tumor specimens are embedded in a solid gel of extracellular matrix (Matrigel) to form 3–4 mm large organoids in the tissue culture medium, supplemented with EGF, FGF, and B27." (PMID 33572835, 2021). "With respect to this, the relation between EGF and other tumor characteristics are worth further investigation including parameters such as human papillomavirus status, histological features, tumor type or tumor grade." (PMID 34115785, 2021). "Additionally, there is a positive feedback loop between macrophages and tumor cells: CSF-1 produced by tumor cells stimulates macrophage motility and secretion of EGF, which in turn supports chemotaxis of tumor cells into blood vessels." (PMID 33919517, 2021). "With highly homologous epidermal growth factor (EGF)-like (EGFL) domains, the members of the EGFL family play crucial roles in growth, invasion, and metastasis of tumors and are closely associated with the apoptosis of tumor cells and tumor angiogenesis." (PMID 33391349, 2020). "It has been shown for tumor cells that part of ligand-bound EGF translocates into the cell nuclei." (PMID 32194412, 2020). "Interestingly, EGF itself is expressed on platelets and its release by tumor-coating platelets was shown to support key features of tumor progression." (PMID 32117229, 2020). "As the tumour progresses, the number of immunosuppressive M2-like TAMs increases, which in turn promotes tumour progression by secreting EGF, VEGF, and MMPs; these factors promote cancer cell proliferation, angiogenesis, and invasion and a pre-metastatic niche, respectively." (PMID 32825277, 2020). "However, there was significant increased expression of EGF in tumour tissues (200.00 ± 28.78) in patients with GG genotype compared to AG genotype (162.31 ± 30.86) and AA genotype (152.50 ± 35.00), p= 0.019." (PMID 32711431, 2020). "However, they can also promote tumor growth by secreting growth factors such as epidermal growth factor (EGF) and transforming growth factor-β1 (TGF-β1)." (PMID 33330508, 2020). "In addition, α-MGT also suppressed the activation of STAT3 induced by IL-6 or EGF, two major growth factors of tumour cells that activate STAT327." (PMID 31980595, 2020). "It has been demonstrated that carvedilol could inhibit the epidermal transformation induced by the tumor promoter EGF." (PMID 33260886, 2020). "Moreover, coculture experiments demonstrate EGFR activation in tumor cells by myofibroblast-derived EGF, resulting in enhanced migratory and invasive properties in vitro." (PMID 32539768, 2020). "Furthermore, it was shown that EGF plays a role in physiological and pathological processes, such as embryogenesis, growth, remodeling, and regeneration of tissues, and neoplasm formation." (PMID 32295556, 2020). "Notably, established SCCs exhibited the increased transcription of EGF, a well-known and typical growth factor involved in the growth and survival of tumor cells." (PMID 32630838, 2020).
tumor (continued). "We took advantage of the bispecific property of LTTs to engineer a new recombinant drug against solid tumors and focused on a different approach that we proposed would simultaneously target both the tumor with EGF and the tumor vasculature with a high-affinity fragment of urokinase." (PMID 32630411, 2020). "EGF acted on vascular endothelial cells in a paracrine manner as a proangiogenic factor to stimulate their migration and morphogenesis for vascular formation, leading to the outgrowth of SCCs to initiate tumor recurrence." (PMID 32630838, 2020). "Average p-values across Calu6, Calu3, H358 and RH2 tumours show enrichment for genes residing in the EGF, NF-κβ, TGF-β, mTOR/PI3K/AKT, integrin, ATM and G1/S checkpoint signalling pathways that was generally greater in tumours exposed to dry powder than aqueous 5AZA." (PMID 32103148, 2020). "However, the heterogenic niche in the TME provides WNT and EGF signals that not only help maintain resident stem cells, but also instruct progenitor cells to revert to a stem cell state, contributing to tumor regeneration and therapy resistance." (PMID 32724475, 2020). "However, upon its interaction with EGFR on tumor cells, EGF induces receptor dimerization and autophosphorylation which activate several downstream kinase cascades." (PMID 32194412, 2020). "This led us to examine whether EGF-stimulated tumor cells elicited NFAT1 induction and whether this was affected by [Ca2+]e restriction on gefitinib-resistant cells." (PMID 32841278, 2020). "The findings in some of these studies have additionally suggested that ZKSCAN3 could modulate several molecules known to play a key role in tumorigenesis and/or tumor progression, such as cyclin D1/D2, EGF, IGF-2, integrin-β4, MMP2/MMP9, NF-κB, and VEGF." (PMID 32824199, 2020). "Studies showed that these two antibodies could inhibit EGFR downstream pathway signalling, thus blocking the proliferation, migration and invasion of tumor cells by competing binding to EGFR with EGF." (PMID 33023595, 2020). "Interestingly, colony-stimulating factor-1 (CSF1) secreted from tumor cells was shown to induce macrophages to produce epidermal growth factor (EGF), which in turn promoted the migration of cancer cells." (PMID 32986017, 2020). "Naamidine A was later tested from the sponge (from different localities) as a selective inhibitor of the epidermal growth factor (EGF) and was found to inhibit human tumor xenografts in mice, as well as displaying antitumour activity that promotes caspase-dependent apoptosis in tumor cells." (PMID 33371188, 2020). "This is confirmed byincreased EGF expression in tumor tissue of G/G genotype." (PMID 32711431, 2020). "The findings suggested that EGF-targeting NPs promoted preferential accumulation at tumor sites." (PMID 32345258, 2020). "Major inducers of EMT in tumor buds are secreted by tumor-associated stromal components; among these inducers are the hepatocyte growth factor (HGF), EGF and TGF-β, which activate intracellular EMT networks involving SMADs, ERK, MAPK and PI3K/AKT signaling pathways." (PMID 33266161, 2020). "The further intravasation of the tumor cells within the blood vessel is also mediated by macrophages; inhibition of the paracrine loop between CSF-1 and EGF through silencing of epidermal growth factor receptor (EGFR) signaling results in blocked intravasation." (PMID 32477352, 2020). "Experimental stimulation of cells with epidermal growth factor (EGF) or CSF-1 determined simultaneous migration of both tumor cells and macrophages even in the case that only macrophages express the receptor for CSF-1 and the receptor of EGF is present strictly in tumor cells." (PMID 32477352, 2020). "In addition, epidermal growth factor (EGF)-induced tumor transformation of mouse epidermal JB6 P+ Cl41 cells was observed." (PMID 33348592, 2020).
tumor (continued). "Although we cannot rule out the possibility of Berberine and Costunolide targeting other signaling pathways, we did demonstrate in this study that in certain tumor cells, like PLC/PRF/5, HT29, and HCC-LM3, Berberine and Costunolide inhibit tumor cell proliferation by modulating EGF signaling." (PMID 32298294, 2020). "Given that stromal cells localised at the tumour-host interface may secrete growth factors such as EGF and FGF225,26, growth factors were considered to constitute a substantial part of the microenvironment that influences the stemness of cancer cells." (PMID 32081957, 2020). "M1 and M2 play opposite roles, while M1 plays anti-tumor effects, M2 phenotype has an immunosuppressive effect and secretes TGF-B, IL-6, IL-1B, EGF, and other cytokines to promote the growth, invasion, and expansion of gliomas by stimulating tumor-related blood vessel formation and tumor metastasis." (PMID 33511267, 2020). "The choice of EGF as the acute signaling stimulus over TGF-β was made, first, to avoid potentially confounding input signals due to the chronic TGF-β treatment used induce EMT, and second, due to the relevance of proliferative EGF signaling and potential in the tumor context." (PMID 33329028, 2020). "Furthermore, TAMs are a source of cytokines such as TGF-β1, STI1 (stress inducible protein 1), EGF (epidermal growth factor), IL-6 (Interleukin 6) and IL-1β (Interleukin 1 Beta) that promote growth, migration and mesenchymal transformation of the tumor cells." (PMID 32570988, 2020). "Until routinely applied anticancer drug combinations are available simultaneously targeting HGF, EGF and NFE2L2 mediated pathways, inhibition of overexpressed DYNLL, TNC, NCL and TMED2 may exert anti-tumor effect on HNSCC beyond their diagnostic role." (PMID 32564264, 2020). "Thus we have established a positive feedback loop where WAVE3/PI3K/TGF-β/EGF signaling axis plays a key role in the regulation of tumor growth in BC." (PMID 33012785, 2020). "CIMAvax-EGF is a therapeutic anticancer vaccine, developed in Cuba under the concept that inducing Epidermal Growth Factor (EGF) deprivation, which involves manipulating an individual’s immune response to release its effector antibodies against EGF, tumour size or its progression, can be reduced." (PMID 32807114, 2020). "Tumor progression involves members of the EGF/neuregulin family, including the EGFR ligand, AR." (PMID 32428872, 2020). "Regarding EGF protein expression in HCC tissue, our present study showed that there was higher concentration of EGF in the tumor tissue (T) (200.00 ± 28.78) in patients with GG genotype compared to AG genotype (162.31 ± 30.86) and AA genotype (152.50 ± 35.00), p= 0.019." (PMID 32711431, 2020). "However, since at a later phase c-Src induces the downregulation of LAR expression, the combined action of both apparently antagonist systems further reduced net DAPK activity, enhancing therefore EGF-dependent tumor cell migration and invasiveness." (PMID 31991573, 2020). "MSC-linked tumor progression is believed to be mediated by growth factors secreted by MSCs, such as vascular endothelial growth factor (VEGF), IL8, transforming growth factor β (TGF-β), epidermal growth factor (EGF) and platelet-derived growth factor (PDGF)." (PMID 32560387, 2020). "They play significant roles both in tumor progression and tumor suppression, participating in evolving processes of tumorigenesis, metastasis, and angiogenesis by producing various signaling molecules, such as EGF, VEGF, MMP-9, IFNs, ILs, etc." (PMID 32850861, 2020). "A rough estimation using these data might suggest the presence of a tumor concentration of EGF 1 log below the concentration used in our in vitro assays." (PMID 31921216, 2019). "Together, these results support our hypothesis that PAX1 is a tumor suppressor that is responsive to environmental factors, such as EGF, and inhibits EGF-induced EMT and malignant phenotypes." (PMID 31235851, 2019).
tumor (continued). "Furthermore, VEGF-A disruption in an EGF-R-deficient background completely inhibits epidermal tumor growth, suggesting that there is an abnormal contribution of the VEGF-A and the EGF pathways in the tumor cells." (PMID 31717527, 2019). "Several signals, such as TGF-β, epidermal growth factor (EGF), and PDGF, produced by the tumor stroma and in particular by CAFs, may be implicated in EMT." (PMID 30959975, 2019). "The model was run under EGF and NGF stimulation conditions in the ALK1174L mutated tumor." (PMID 31480495, 2019). "While CD109 has the ability to inhibit TGF-β-induced EMT and to enhance migration of cancer cells, it may promote tumor initiation and metastasis by enhancing the EGF or the JAK-STAT3 pathway." (PMID 31695056, 2019). "Maybe this could be partly explained by the ability of PDAC to develop distant metastases, which could be enhanced by the molecules released by the poorly differentiated tumor, including epidermal growth factor, E-cadherin." (PMID 31781499, 2019). "EGF levels ranges between 20 pg/μg tumor (in B16.OVA) to 160 pg/μg tumor (in Hepa129)." (PMID 31921216, 2019). "Moreover, mice injected with NSCLC cells ectopically expressing EGF had a shorter tumor-free survival time than those xenografted with control NSCLC cells." (PMID 30177836, 2019). "Moreover, TAMs release epidermal growth factor and other epidermal growth factor receptor family ligands to promote tumour cell proliferation and migration." (PMID 30824727, 2019). "EGF has been reported to induce focal adhesion disassembly and enhance tumour cell motility through EGFR-activated E-cadherin endocytosis, and SGSM2 has been reported to interact with RAB family proteins, who function in recycling of vacuoles between the early endosome and plasma membrane." (PMID 30744493, 2019). "Additionally, this assay has the potential to be optimized with other tumor promoters such as hepatocyte growth factor, epidermal growth factor, and phorbol esters, as well as with complete carcinogens such as BaP." (PMID 31311976, 2019). "Targeting S100 proteins may prevent EGF induced tumor cell growth and metastasis and can complement trastuzumab therapy." (PMID 30736768, 2019). "So, we wondered whether EGF-induced 6PGD Y481 phosphorylation is involved in the resistance of tumor cells to IR." (PMID 30824700, 2019). "Indeed, the higher the concentration of EGF in the LN, the higher the number of proliferating cells in the tumor, and therefore the more responsive the tumor will be to anti-PD-1/PD-L1 therapy." (PMID 31157216, 2019). "EGF signaling plays a pivotal role in tumor growth and progression in CRC." (PMID 31683810, 2019). "In mice injected with EGF-treated or PN-1-overexpressing MCF-7 cells, bigger sized tumors with clear boundaries (arrows) were found in the lungs and livers, while only small tumor masses were scattered in the lungs and livers of EGF-treated and PN-1 knocked-down MCF-7 cells group and control group." (PMID 31501409, 2019). "Because tumor cells are exposed to nutrients and various growth factors, such as epidermal growth factor (EGF), fibroblast growth factor (FGF), and vascular endothelial growth factor (VEGF), mTOR signaling activation is promoted in the cells under normoxic conditions." (PMID 31929797, 2019). "The normoxic stabilization of HIF1α at the protein level was found in various tumor cell lines after the application of several growth factors (e.g., EGF or insulin) or fetal bovine serum only in the presence of the amino acid glutamine and as a result of glutaminolysis." (PMID 31554283, 2019). "Therefore, we first sought to uncover how EGR1 permits tumor progression in EGF-treated HNSCC cells." (PMID 30845713, 2019). "We further performed Gene Set Enrichment Analysis (GSEA) and found that the differentially expressed genes between I P and I NP tumors were significantly overrepresented in signatures associated with ‘Hypoxia’, ‘EGF signaling’, ‘HRAS oncogenic’ and ‘Tumor angiogenesis’." (PMID 31039818, 2019).
tumor (continued). "Among them, EGF displayed the highest correlation with ITGA5 in SKOV3 tumor cells." (PMID 30710055, 2019). "Therefore, inhibition of either CSF-1 or EGF signaling pathway perturbs the migration of both cell types and reduces the numbers of circulating tumor cells as well." (PMID 31300030, 2019). "M2 macrophages participate in tumor growth by releasing proangiogenic cytokines and growth factors, e.g. Epidermal Growth Factor (EGF), Vascular Endothelial Growth Factor (VEGF), Platelet-Derived Growth Factor (PDGF), Colony Stimulating Factor-1 (CSF-1), and basic Fibroblast Growth Factor (βFGF)." (PMID 31480382, 2019). "HIF-1 activates many target genes, and HIF-1-regulated gene products (i.e., vascular endothelial growth factor, epidermal growth factor, erythropoietin, glucose transporters, and glycolytic enzymes) facilitate tumor survival, proliferation, invasion, and metastasis." (PMID 30719182, 2019). "It has been reported that miR-30 could target Wnt/β-catenin, EGF/Src, Myc, Rab18 and other signaling to inhibit tumor growth." (PMID 31382411, 2019). "In addition, in vivo studies performed administering RSV/DTX EGF LPNs intravenously in mice bearing lung cancer showed a significant inhibition of tumor growth and a notable reduction of its size." (PMID 31349656, 2019). "Low intratumoral MAPK/RAS/RAF signaling activity, suggesting low proliferative activity of the tumor cells and thus favorable prognosis, may lead to compensatory EGF excretion in tumor cells." (PMID 31358848, 2019). "Interestingly, it is also possible to eradicate the tumor if the value of EGF concentration in the LN is above 0.9 and the Ksupp value is below 0.3." (PMID 31157216, 2019). "However, Epidermal Growth Factor (EGF) promotes tumor progression even with significant EGR1 upregulation." (PMID 30845713, 2019). "Extracellular galectin 3 may influence tumour progression by impeding the endocytosis of key receptors, including TGFβ and EGF, while at the same time inducing endocytosis of β1 integrins." (PMID 29666124, 2018). "The tumor sphere assay was performed by seeding MCF-7 cells in Dulbecco’s Modified Eagle Medium/Nutrient Mixture F-12 (DMEM/F12) media containing the growth supplements Epidermal growth factor (EGF), basic fibroblast growth factor (bFGF), and B27." (PMID 29914089, 2018). "Cancer cells that encounter a combination of different signaling molecules like PDGF, HGF, TGF-β1, or EGF among many others secreted by the complex tumor microenvironment orchestrate the gene expression of cancer cells for instance by upregulation of transcription factors like snail, twist, or zeb1." (PMID 30347648, 2018). "We next sought to determine if biasing EGFR signaling could change the EGF response of primary tumor cells from proliferative to apoptotic." (PMID 30250119, 2018). "It is unclear whether the EGF recombinant protein is able to penetrate or diffuse efficiently into the tumor tissue when cultured on a sponge." (PMID 29861851, 2018). "The finding suggests that leakage of EGF from tumor microenvironment by 4D3 might result inhibition of stem cell phenotype of cancer cells." (PMID 30647838, 2018). "It has been suggested that tumor microenvironment and growth factors such as transforming growth factor-β (TGFβ), epidermal growth factor (EGF), platelet-derived growth factor (PDGF) has a dramatic effect on epithelial phenotype and in promoting motility and invasiveness via the induction of EMT." (PMID 30619759, 2018). "Furthermore, upregulation of CSF1 by tumor cells stimulates macrophage recruitment and the production of epidermal growth factor (EGF), which in turn promotes tumor cell migration." (PMID 29594035, 2018). "Hence, a myriad of oncogenic signaling pathways including Wnt, G-protein coupled receptors (GPCRs), and epidermal growth factor (EGF) hijack the Hippo tumor-suppressor pathway to positively regulate YAP/TAZ to promote tumorigenesis and progression." (PMID 29415512, 2018).